CLN3 (CLN3 lysosomal/endosomal transmembrane protein, battenin)
Diseases named in the same sentence as CLN3 in open-access papers (continued):
Sharing a sentence is not in itself a finding about the gene and the disease.
Batten disease (continued). "CLN3 disease (OMIM #204200), also known as juvenile neuronal ceroid lipofuscinosis or Batten disease, is the most frequent of the neuronal ceroid lipofuscinoses (NCLs)." (PMID 29392585, 2018). "Experiments with Drosophila melanogaster as a relatively simple model organism for studying Batten disease showed that the fruit fly cells lacking CLN3 are hypersensitive to oxidative stress yet they respond normally to other physiological stresses." (PMID 33137890, 2020). "Our results suggest that there is not a robust biomarker for CLN3-Batten disease in commonly tested hematological measurements." (PMID 30086172, 2018). "Although significant advances in the treatment of other lysosomal storage disorders have been made over the last decade, therapeutics for CLN3-Batten disease do not currently exist." (PMID 30086172, 2018). "Studies of fibroblasts from Batten disease patients show elevated lysosomal pH and yeast lacking the CLN3 protein homolog, Btn1p, have abnormal vacuolar pH in the early phases of growth." (PMID 19440452, 2008). "It is worth noting that the absolute levels of ferritin, even in control mice, varied substantially between these two studies, though when combined with the interaction of genotype and colony revealed in our study, this suggests that ferritin may not be a consistent biomarker of CLN3-Batten disease." (PMID 30086172, 2018). "Other authors not only proved the interaction between proteins CLN3 and Na/K ATPase ATP1A1, but also showed that functions of ATP1A1 as a pump were not significantly affected in patients with Batten disease." (PMID 30621751, 2018). "Lastly, for Batten disease patients, the authors found increased level of GPI in their cerebrospinal fluid, then it would be of interest to understand how those GPDs are released from lysosomes into cerebrospinal fluid in the absence of a functional CLN3." (PMID 39872513, 2023).
neuronal ceroid lipofuscinosis (36 papers, 2011 to 2025). "In recent years, there is growing recognition that genes initially associated with severe LSDs, such as neuronal ceroid lipofuscinosis (CLN3 and MFSD8) and mucopolysaccharidosis type IIIC (HGSNAT), can also cause non-syndromic retinal dystrophy." (PMID 38863195, 2024). "For example, CLN3 disease, one form of neuronal ceroid lipofuscinosis, is caused by variants in the ubiquitously expressed CLN3 gene." (PMID 36675282, 2023). "Mutations in CLN3 (ceroid lipofuscinosis neuronal 3) cause a juvenile form of NCL, which is the most common subtype of the disease." (PMID 30717401, 2019). "Retinal degeneration and visual impairment are the first signs of juvenile neuronal ceroid lipofuscinosis caused by CLN3 mutations, followed by inevitable progression to blindness." (PMID 26450516, 2015). "Juvenile neuronal ceroid lipofuscinosis (JNCL) is caused by mutations in the CLN3 gene, which encodes for a putative lysosomal transmembrane protein with thus far undescribed structure and function." (PMID 25051496, 2014). "After we carried out this work, a form of vacuolar myopathy was associated to CLN3, implicated in neuronal ceroid lipofuscinosis, ranked 343rd for vacuolar myopathies." (PMID 25353622, 2014). "In humans, mutations in CLN3 cause a juvenile form of neuronal ceroid lipofuscinosis, a lysosomal storage disease." (PMID 24705017, 2014). "The accumulation of the autophagy-lysosomal pathway components in a cell is observed in many neurodevelopmental diseases; for example, variants in CLN3 cause neuronal ceroid lipofuscinosis and a specific accumulation of lysosomes in the perinuclear region have also been detected in CLN3 deficits." (PMID 40401444, 2025). "Furthermore, the human CLN3 protein is associated with Neuronal Ceroid Lipofuscinosis (NCL), which is one of the most common types of neurodegenerative disorders in children." (PMID 40136540, 2025). "While variants in genes associated with neuronal ceroid lipofuscinosis (CLN3 (OMIM 607042), CLN5 (OMIM 608102), and MFSD8/CLN7 (OMIM611124)) typically lead to severe neuronal dysfunction and lysosomal storage in neurons and the peripheral tissues, some variants present with isolated retina disease." (PMID 35226187, 2022). "To this end, we isolated microglia from Cln3Δex7/8 homozygous knock-in mice (hereafter referred as Cln3KI/KI), which express the most common loss-of-function allelic variant of the lysosomal gene Cln3 found in patients with juvenile-forms of neuronal ceroid lipofuscinosis (NCL)." (PMID 32579115, 2020). "Juvenile neuronal ceroid lipofuscinosis (JNCL) is caused by mutations in the CLN3 gene." (PMID 29470438, 2018). "We interrogated auditory sensory memory capabilities in individuals with CLN3 disease (juvenile neuronal ceroid lipofuscinosis), specifically for the feature of “duration” processing." (PMID 38183037, 2024). "Accordingly, the names CLN3-related neuronal ceroid lipofuscinosis or CLN3-disease sometimes have been used for this malady." (PMID 33137890, 2020). "Juvenile neuronal ceroid lipofuscinosis, now classified as CLN3 disease, represents the most common form of the neuronal ceroid lipofuscinoses (NCLs), a family of fatal inherited pediatric neurodegenerative disorders." (PMID 33006978, 2020). "We study the role of btn1, the orthologue of a human gene that underlies an early onset neurodegenerative disease (juvenile CLN3 disease, neuronal ceroid lipofuscinosis (NCLs) or Batten disease) in the fission yeast Schizosaccharomyces pombe." (PMID 28357272, 2015). "However, there are results of experiments indicating the reduction in the level of glutathione peroxidase in the Cln3 knock-in (Cln3 (Deltaex7/8)) mouse model of neuronal ceroid lipofuscinosis." (PMID 33578654, 2021). "Loss-of-function mutations in CLN3, an endolysosomal transmembrane protein, result in a form of LSD called neuronal ceroid lipofuscinosis (NCL)." (PMID 32708198, 2020).
neuronal ceroid lipofuscinosis (continued). "The article contains raw and analyzed data related to the research article “Neuronal ceroid lipofuscinosis genes, CLN2, CLN3, CLN5 are spatially and temporally co-expressed in a developing mouse brain”." (PMID 27508227, 2016). "Neuronal ceroid lipofuscinosis genes: CLN1, CLN2, CLN3, CLN5 were examined in neuronal tissue during mouse brain development." (PMID 27508227, 2016).
lysosomal storage disorder (20 papers, 2006 to 2026). "CLN3 disease is a lysosomal storage disorder associated with fatal neurodegeneration that is caused by mutations in CLN3, with most affected individuals carrying at least one allele with a 966 bp deletion." (PMID 36453132, 2022). "Mutations in CLN3 lead to photoreceptor cell loss in CLN3 disease, a lysosomal storage disorder characterized by childhood-onset vision loss, neurological impairment, and premature death." (PMID 33547385, 2021). "Juvenile neuronal ceroid lipofuscinosis (JNCL) is a lysosomal storage disorder caused by mutations in the CLN3 gene." (PMID 29470438, 2018). "Juvenile Neuronal Ceroid Lipofuscinosis (JNCL) is a lysosomal storage disease caused by an autosomal recessive mutation in CLN3 that leads to vision loss, progressive cognitive and motor decline, and premature death." (PMID 24736558, 2014). "Mutations in the Cln3 gene leads to a lysosomal storage disorder associated with the accumulation of lipopigment-laden vesicles." (PMID 16670020, 2006). "Since JNCL is a lysosomal storage disorder with alterations in endosomal/lysosomal system, the localization of the intracellular CTX in lysosomes was studied using staining with anti-LAMP-1 antibodies in CTX-A488 labeled WT and Cln3Δex7/8 cells." (PMID 29470438, 2018). "Autophagy has been reported to be blocked during the pathogenesis of several lysosomal storage diseases, including CLN3 and CLN10." (PMID 22536393, 2012). "The foundation worked with Thomson Reuters to gather referenced CLN3 gene and CLN3 protein information and with painstaking attention to detail, validated the information together with experts in CLN3 disease, lysosomal storage disease, and lysosome/endosome biology." (PMID 31568712, 2019). "One unusual feature of all of these lysosomal storage disease models (CLN1, CLN2, and CLN3 disease) is patchy ENS degeneration." (PMID 41430350, 2025).
retinal degeneration (14 papers, 2012 to 2023). Degeneration of the retina. "In that study, 5 patients from a total of 123 retinal degeneration patients had a CLN3 mutation with 4 RCD and 1 CRD phenotype." (PMID 36964447, 2023). "Analysis of these reports suggests that it is more likely that the 1 kb homozygous deletion is associated with the syndromic CLN3 phenotype, while compound heterozygous mutations are more likely to be found in the isolated retinal degeneration phenotype." (PMID 36964447, 2023). "For example, the introduction of 1.02-kb deletion in the mouse cln3 gene causes the retina degeneration only in the second half of the animals’ life, and all the other symptoms are manifested in a mild form." (PMID 33137890, 2020). "Enigmatically, LAMP‐1 expression was markedly—andrepeatedly—elevated in the CD20 compartment of the CLN3‐associated retinal degeneration patient." (PMID 32685355, 2020). "Mutations in CLN3 are classically associated with CLN3 disease where retinal degeneration is followed by mental and physical deterioration and premature death." (PMID 31568712, 2019). "Under these ‘low light’ conditions, CLN3-deficient mice showed a strong retinal degeneration, microglial activation, deposition of autofluorescent material and transcriptomic changes compared to wild-type animals." (PMID 30042155, 2018). "Notably and consistent with an important role of CLN3 in outer retina homeostasis, in the non-syndromic form of retinal degeneration caused by other mutations in CLN3, the initial defects in the retina are restricted to the photoreceptor–RPE complex." (PMID 33547385, 2021). "Given the very mild retinal degeneration in young Cln3Δex7/8 mice, we sought to establish a light-damage paradigm that could distinguish CLN3-deficient animals from controls." (PMID 30042155, 2018). "Pre-postmortem stage affected retina have only been studied in CLN3-deficient mouse models, where retinal degeneration is first indicated by widespread accumulation of this characteristic autofluorescent storage material in the photoreceptor and ganglion cell layers." (PMID 26450516, 2015). "Ultimately, if RPE dysfunction and POS phagocytosis defect are central to photoreceptor cell loss and retinal degeneration in CLN3 disease and CLN3-associated non-syndromic retinal degeneration, RPE cells may be a crucial gene therapy target for these blinding disorders." (PMID 33547385, 2021). "The mechanism for retinal degeneration in CLN3 disease is yet to be understood." (PMID 36964447, 2023). "Although it is well established that retinal damage is responsible for vision loss in CLN3 disease, the primary cellular and molecular mechanisms leading to retinal degeneration in CLN3 disease are not known." (PMID 33547385, 2021). "LAMP‐1 expression did not change over time: expression of LAMP‐1 was stable in all lymphocyte compartments (P = .53 for CD4, P = .11 for CD8, P = .14 for the CD20 without the CLN3‐associated retinal degeneration subtype)." (PMID 32685355, 2020). "Our findings indicate that exposure to specific light conditions accelerates CLN3-dependent retinal degeneration, and that immunomodulation by minocycline could be a possible treatment option to delay vision loss in jNCL patients." (PMID 30042155, 2018). "CLN3 literature implies that syndromic CLN3 disease (mostly homozygous variant) is characterized by CRD with childhood onset and rapid disease progression, while the isolated retinal degeneration case (mostly compound heterozygous variant) is rather a RCD with later onset and slower progression." (PMID 36964447, 2023). "Thirdly, the presence of a non-syndromic retinal disease in patients with certain mutations in CLN3 showing retinal degeneration without additional progression of CLN3 disease further supports that the retina seems to be the most vulnerable organ to CLN3 deficiency." (PMID 36438942, 2022).
retinal degeneration (continued). "Interestingly, while spastic paraparesis is not a symptom of (classical‐protracted) CLN3 disease, it is present in the CLN3‐associated retinal degeneration patient included in this study." (PMID 32685355, 2020). "Subsequent studies of the CD1 background mice indicated additional retinal degeneration genetic loci, independent of the Cln3 locus, leaving the precise details of retinal degeneration as a result of the Cln3Δex7/8 mutation in question (Ruether, unpublished data)." (PMID 22701626, 2012). "This would be consistent with the possibility that delayed phagosome degradation due to loss of Rep1 or CLN3 may not alone cause retinal degeneration, but could compromise RPE function sufficiently to increase the susceptibility of the neural retina to cell autonomous defects." (PMID 26450516, 2015).
Blindness (10 papers, 2014 to 2026). Blindness is the condition of lacking visual perception defined as a profound reduction in visual perception. "It is also important to consider ceroid lipofuscinosis in patients with blindness of unknown cause and in older children—especially CLN3." (PMID 36576693, 2023). "We conduct a pilot study of an assistive device in children with CLN3 disease, a multisystemic pediatric blindness and neurodegenerative condition." (PMID 41933359, 2026). "While sleep issues are known sequela of both blindness and dementia and have been previously reported in CLN3 disease, the very high prevalence reported here suggests that it may be a characteristic aspect of the disease that potentially contributes to other cognitive and behavioral problems." (PMID 38500130, 2024). "Onset of vision loss was only slightly later in protracted CLN3 disease (mean age at onset 7.1 years, range 5–10 years, n = 9) similarly resulting in blindness within a few years after onset (data not shown) while cognition was unaffected around diagnosis and remained normal until adulthood." (PMID 29392585, 2018). "The relative lack of visual impairment in all CLN3-deficient mice contrasts with human juvenile NCL where degenerating vision is the lead symptom, and progression to blindness tends to be rapid, although disease does not tend to become apparent until later childhood around 5–10 years of age." (PMID 26450516, 2015).
epilepsy (8 papers, 2014 to 2025). A brain disorder characterized by episodes of abnormally increased neuronal discharge resulting in transient episodes of sensory or motor neurological dysfunction, or psychic dysfunction. "More recent careful studies, however, show that myoclonus is not a predominant feature of classic CLN3 disease, and that the epilepsy type associated with classic CLN3 disease is best classified as a combined focal and generalized epilepsy." (PMID 37039534, 2023). "Patients with a CLN3 mutation are also prone to recurrent seizures,epilepsies, vision impairment and occasionally psychosis." (PMID 27163203, 2016). "Using the new International League Against Epilepsy nomenclature, protracted CLN3 disease is an epilepsy syndrome with progressive neurologic deterioration, rather than a DEE." (PMID 37039534, 2023). "This case series highlights that the epilepsy type of protracted CLN3 disease is also a combined focal and generalized epilepsy." (PMID 37039534, 2023). "Epilepsy has been described in patients with CLN3 disease and CLN3 has been mapped as an “epilepsy gene”." (PMID 37573956, 2023).
cognitive decline (7 papers, 2018 to 2026). "CLN3 disease, the most common form of the Neuronal Ceroid Lipofuscinoses (NCLs), causes progressive cognitive decline and language impairment in humans." (PMID 42282513, 2026). "These inconsistencies in the manifestation of the onset of cognitive decline were taken to highlight the importance of careful acquisition of patient history in those suspected to have CLN3 disease." (PMID 38183037, 2024). "In this study, we evaluated timing and severity of cognitive decline in CLN3 disease in literature-derived patients supplemented with a representative referral center cohort." (PMID 29392585, 2018). "Onset of cognitive decline at a mean age of 6.8 years (range 2–13 years, n = 19) paralleled onset of visual deterioration (mean age of 6.4 years, range 4–9 years, n = 81) in patients with classical CLN3 disease." (PMID 29392585, 2018). "Onset of cognitive decline at a mean age of 6.8 years (range 2–13 years, n = 19) paralleled onset of visual deterioration at a mean age of 6.4 years (range 4–9 years, n = 81) as supported by an early decline in IQ scores in classical CLN3 disease." (PMID 29392585, 2018). "The aim of our study is to delineate timing of cognitive decline in CLN3 disease." (PMID 29392585, 2018). "Early neurocognitive functioning in CLN3 disease was analyzed using age at onset of visual and cognitive decline and IQ scores from literature-derived patient descriptions, supplemented with IQ scores and school history from a retrospective referral center cohort." (PMID 29392585, 2018). "Indeed, cognitive decline may not be apparent until well into adulthood in the protracted form of CLN3 disease displayed by a minority of patients." (PMID 29392585, 2018).
Cognitive impairment (7 papers, 2018 to 2026). Abnormal cognition is characterized by deficits in thinking, reasoning, or remembering. "Due to a mutation in CLN3, there are clear indications of cognitive impairment, depressed mood, anxiety, loss of learning abilities, attention, loss of memory, feeding, and adaptive skills." (PMID 35139088, 2022). "CLN3 disease exerts devastating neurological and neurodegenerative effects upon the CNS resulting in visual impairment, seizures, and cognitive deficits, ending in a premature death in the second or third decade of life." (PMID 41430350, 2025). "Our results show that in classical CLN3 disease cognitive deficits are consistently present around the time of diagnosis." (PMID 29392585, 2018). "Furthermore, the universal presence of early learning problems in classical CLN3 patients underscores that early intellectual impairment reflects actual functional impairment in daily life." (PMID 29392585, 2018). "As such, the relationships between cognitive impairments and other clinical features of CLN3 disease are not yet well understood." (PMID 38183037, 2024).